PDAP1 (PDGFA associated protein 1)
Description:
Enhances PDGFA-stimulated cell growth in fibroblasts, but inhibits the mitogenic effect of PDGFB.
Synonyms: PAP; PAP1; HASPP28
Tractability: Antibody: its Gene Ontology location is reachable by antibodies, with high confidence; the Human Protein Atlas places it where antibodies can reach. PROTAC: UniProt records ubiquitination sites on it; ubiquitination databases record sites on it; its protein half-life has been measured.
Gene: Protein-coding gene on chromosome 7 (99,392,048 to 99,408,665, reverse strand). Ensembl gene ENSG00000106244.
Subcellular location (Human Protein Atlas): Cytosol; Plasma membrane
Pathways (Reactome):
Immune System: Neutrophil degranulation
Gene Ontology:
Molecular function: protein binding; RNA binding
Biological process: signal transduction
Cellular component: cytosol; plasma membrane; extracellular region; ficolin-1-rich granule lumen
Genetic constraint (gnomAD): Loss-of-function variants: 13 observed, 22.12 expected, observed/expected ratio (o/e) 0.59, 90% interval 0.38 to 0.93. The upper end of that interval is the gene's LOEUF score, 0.93, which puts it in group 3 of 6, group 1 being the genes least tolerant of losing a copy. Missense variants: 126 observed, 191.01 expected, observed/expected ratio (o/e) 0.66, 90% interval 0.57 to 0.76. Synonymous variants: 67 observed, 73 expected, observed/expected ratio (o/e) 0.92, 90% interval 0.75 to 1.12.
Homologues: Orthologues: chimpanzee PDAP1 (100% identical), dog PDAP1 (99% identical), guinea pig PDAP1 (99% identical), pig PDAP1 (98% identical), mouse Pdap1 (97% identical), rabbit PDAP1 (97% identical), rat Pdap1 (96% identical), tropical clawed frog pdap1 (75% identical), zebrafish pdap1b (69% identical), Drosophila melanogaster CG11444 (47% identical), Drosophila melanogaster CG4438 (39% identical).
Diseases named in the same sentence as PDAP1 in open-access papers:
PDAP1 is named in the same sentence as 16 diseases in open-access papers, as found by Europe PMC text mining. Sharing a sentence is not in itself a finding about the gene and the disease. The quoted sentences say what the papers report.
breast carcinoma (3 papers, 2024). "In addition, it includes several ferroptosis repressors that might be promising candidates for breast cancer therapy, of which one representative, PDAP1 (PDGFA-associated protein 1), was validated in a xenograft tumor model." (PMID 38811541, 2024). "Collectively, these results suggest that PDAP1, which belongs to the “JB2 Up” subset, is a ferroptosis suppressor in basal‐like breast cancer and a potential therapeutic target." (PMID 38441406, 2024). "We also identified and validated a set of 24 selective ferroptosis versus apoptosis biomarkers and showed that depletion of PDAP1, a representative gene of the GGS, induced ferroptotic cell death and inhibited tumor growth in the xenograft model of basal‐like breast cancer." (PMID 38441406, 2024).
breast tumor (2 papers, 2024). "Depletion of one representative, PDGFA‐assaociated protein 1(PDAP1), is found to suppress basal‐like breast tumor growth in a mouse model." (PMID 38441406, 2024).
glioma (2 papers, 2018 to 2024). A benign or malignant brain and spinal cord tumor that arises from glial cells (astrocytes, oligodendrocytes, ependymal cells). "Indeed, PDAP1 was shown recently to be an effector of PDGR signaling in glioma cells and was associated with proliferation and disease progression, highlighting PDAP1 as a potential therapeutic target." (PMID 29656114, 2018).
leukemia (1 paper, 2018). A malignant (clonal) hematologic disorder, involving hematopoietic stem cells and characterized by the presence of primitive or atypical myeloid or lymphoid cells in the bone marrow and the blood. "We suggest that the role of PDAP1 in the cellular response to DNA-damaging agents should be investigated further in leukemia cells because PDAP1 might represent an interesting novel therapeutic target for chemosensitization." (PMID 29656114, 2018). "However, with respect to daunorubicin, our data from HeLa cells indicate that STAT6, and in particular PDAP1, appear to function in the cellular response to daunorubicin and warrant further investigation in leukemia cells." (PMID 29656114, 2018).
viral infection (1 paper, 2021). "Interestingly, many of the candidate proteins have only limited functional links to viral infection and immune regulation and were not previously known to interact with NAs (e.g., c8orf88, DTYMK, KIF2A, PDAP1, PDIA5, TAOK1, TAOK2, and VRK1)." (PMID 34853303, 2021).
cancer (9 papers, 2020 to 2025). A tumor composed of atypical neoplastic, often pleomorphic cells that invade other tissues. "Based on the phenome‐wide mediation MR analyses from the Sections 2.3 and 2.4, both the eQTL and pQTL of PDAP1, previously reported to be related to cancer, were associated with several cardiometabolic traits that reduce lifespan." (PMID 40211681, 2025). "PDAP1 was found associated with different types of cancers, hinting at a role in the regulation of cell proliferation." (PMID 35143476, 2022). "Furthermore, down-regulation studies have implicated Pdap1 in cell survival and apoptosis resistance of cancer cell lines." (PMID 32609329, 2020). "Gene expression of Pdap1, a multifunctional protein, is increased in cancer and plays a role in DNA replication, repair, and invasion." (PMID 39165691, 2024). "These suggested the elevation of PDAP1 might influence lifespan via metabolic effects in addition to cancer." (PMID 40211681, 2025). "Furthermore, the GGS is a unique source of novel ferroptosis regulators, such as PDAP1, which might be used as targets for cancer therapy." (PMID 38441406, 2024). "Mediation analysis suggested that PDAP1 decreased longevity via decreased SHBG, increased waist circumference, blood pressure, smoking, and alcohol consumption in addition to cancer." (PMID 40211681, 2025). "Importantly, we showed that PDAP1 depletion induced ferroptotic death both in vitro and in vivo, possibly through the AKT-mTOR-SREBP1-SCD1 axis, further demonstrating the power of the described pipeline and the potential of the discovered candidate targets for cancer therapy." (PMID 39310772, 2024). "However, the potential roles of those specific proteoforms of PDAP1 and CALM1 in cancer are still not clear." (PMID 36542699, 2022).
tumor (4 papers, 2023 to 2024). "Additionally, higher expression levels of PDAP1 and CHRNA5 were found in patients who experienced new tumor events after initial treatment." (PMID 37509183, 2023).
PDAP1 also shares sentences with these, for which no sentence is quoted: acute lymphoblastic leukemia (1 paper); B cell lymphoma (1); Cerebellar atrophy (1); cholangiocarcinoma (1); colorectal cancer (1); diabetes (1); gastric cancer (1); multiple sclerosis (1); rectal carcinoma (1).